RAD51 (RAD51 recombinase)
Diseases named in the same sentence as RAD51 in open-access papers (continued):
Sharing a sentence is not in itself a finding about the gene and the disease.
endometrial cancer (16 papers, 2014 to 2026). Primary or metastatic malignant neoplasm involving the endometrium (mucous membrane that lines the endometrial cavity). "An association was confirmed between RAD51 G135C and G172T polymorphisms and endometrial cancer progression, assessed by the histological grades." (PMID 24930116, 2014). "In the presented study, the PCR–RFLP technique was used to screen 630 endometrial cancer patients for RAD51 polymorphisms." (PMID 24930116, 2014). "Some correlation was observed between the RAD51 G135C and G172T polymorphisms, and endometrial cancer invasiveness." (PMID 24930116, 2014). "The RAD51 135C allele was associated with a significantly increased risk of endometrial cancer in Poland." (PMID 24930116, 2014). "In the present work, a relationship was identified between RAD51 G135C polymorphism and the incidence of endometrial cancer." (PMID 24930116, 2014). "In the presented study, the role of polymorphisms was studied in DNA DSB repair RAD51 gene, the polymorphisms being regarded as risk factors for endometrial cancer in a case setting." (PMID 24930116, 2014). "A tendency towards a decreased risk of endometrial cancer was observed with the occurrence of combined G135C–G172G genotype of RAD51 polymorphism." (PMID 24930116, 2014). "The study of RAD51 G135C polymorphism in Polish population identified a haplotype associated with endometrial cancer." (PMID 24930116, 2014). "A haplotype analysis was performed to estimate the interaction between the G135C polymorphism of RAD51 gene, as well as between the G172T polymorphism of RAD51 and endometrial cancer occurrence." (PMID 24930116, 2014). "In the reported study, the G135C polymorphism of RAD51 gene and G172T of RAD51, were correlated with endometrial carcinoma progression." (PMID 24930116, 2014). "The RAD51 polymorphisms were found to be associated with various cancer diseases but little data are available on the association or its lack in endometrial cancer." (PMID 24930116, 2014). "In view of the potentially significant role of the DNA repair machinery for more intensive cancer development, it is important to know whether the RAD51 gene polymorphism can account for the appearance of endometrial cancer occurrence." (PMID 24930116, 2014). "The results support the hypothesis that RAD51 G135C and G172T polymorphisms may be associated with endometrial cancer occurrence and/or progression." (PMID 24930116, 2014). "In the literature, many reports confirm that RAD51 G135C and G172T polymorphisms may be associated with the development of certain types of cancers, but little is known about their association with endometrial carcinoma." (PMID 24930116, 2014). "On this basis, the overexpression of recombination protein A (Rad51) in endometrial cancer is a representative example of YAP/TAZ-mediated gene expression." (PMID 35309903, 2022). "It has also been reported that OTUB2 promotes homologous recombination repair of endometrial carcinoma through YAP/TAZ mediated Rad51 expression, which provides a potential therapeutic target for endometrial carcinoma." (PMID 35850645, 2022). "Thus, RAD51 expression is indicated to be regulated in a PTEN-independent manner in endometrial cancers." (PMID 24625059, 2014). "Recently, an adaptation to ovarian and endometrial cancer FFPE tissues, entitled RAD51-FFPE, was developed." (PMID 35267439, 2022). "Using endometrial cancer cellular models with known PTEN status, we evaluated their homologous recombination (HR) functionality by RAD51 foci formation assay." (PMID 28886696, 2017).
head and neck cancer (16 papers, 2014 to 2026). A primary or metastatic malignant neoplasm affecting the head and neck. "The role of RAD51 gene polymorphisms with the development of head and neck cancer (HNC) and esophageal cancer (EC) remains controversial." (PMID 31886162, 2019). "First, this is the first report not only to analyze two polymorphisms in Rad51 gene (G135C and G172T) and cancer risk in different cancer forms, but also to identify the G172T polymorphism as a risk factor for head and neck cancers." (PMID 24475258, 2014). "Only a few papers studied RAD51 expression and its relation to treatment success in head and neck cancer." (PMID 36837562, 2023). "In turn in the case of rs2619679 polymorphism in RAD51, it was shown that it does not correlate with the risk of head and neck cancer." (PMID 31186630, 2019). "The genetic variations of RAD51 and its paralogs may contribute to the development of cancer, as has been shown in the case of breast, ovarian, endometrial, colorectal, and head and neck cancer and acute leukemia." (PMID 26339569, 2015). "It is suggested the improper regulation of Rad51 may affect tumorigenesis, as Rad51 has been shown to be over-expressed in a number of cancer phenotypes, including esophageal, pancreatic, lung, leukemia, and head and neck cancers." (PMID 24795863, 2014). "Haplotype analysis for XRCC1 (rs3213245, rs1799782, rs25489 and rs25487), RAD51 (rs1801320, rs1801321) and NBN (rs1805787, rs1805794) and radiation-induced oral mucositis and skin reactions in head and neck cancer patients." (PMID 24594932, 2014). "The literature data on RAD51 as a possible surrogate marker for radiosensitivity in head and neck cancer are, to our knowledge, not available." (PMID 36837562, 2023). "Nevertheless, this was recently discussed in the context of head and neck cancer cells, and requires further investigation in UM cell lines, particularly employing DSB repair-specific assays or end-points (e.g., γH2AX/53BP1 or RAD51 foci analysis)." (PMID 32481544, 2020).
leukemia (14 papers, 2011 to 2024). A malignant (clonal) hematologic disorder, involving hematopoietic stem cells and characterized by the presence of primitive or atypical myeloid or lymphoid cells in the bone marrow and the blood. "Overexpression of BLM and RAD51 facilitates HRR and thereby causes resistance of BCR/ABL-positive leukemia cells to DNA damaging drugs." (PMID 38421735, 2024). "Combining treatment with DOCK2 knockdown and DDR inhibitors such as CHK1 inhibitor MK876, WEE1 inhibitor MK1775, and RAD51 inhibitor 1302 significantly enhanced the sensitivity of mice with FLT3-ITD mutant leukemia cells to cytarabine." (PMID 36250020, 2022). "As a transcript factor, EBF1 over-expression increases DNA damage by directly targeting RAD51 in leukemia, while EBF1 knockdown promotes cell proliferation and migration by increasing CD133, Oct3/4, and TFF1 expression in CCA." (PMID 32676457, 2020). "Analysis of leukemia-prone polymorphic alleles (XPA A23G, XPD Lys751Gln, XRCC1 Arg399Gln, XRCC3 Thr241Met, and RAD51 G135C) revealed an XPD and XRCC3-deficient heterozygous pre-SCT patient with normal alleles for XPA, XRCC1, and RAD51 DNA repair functions." (PMID 21951951, 2011). "Recent study discovered that the combination therapy of glycolytic inhibitor 2-deoxy-D-Glucose and Rad51 specific inhibitor has shown increased efficacy for targeting leukemias, indicating increasing the efficacy of glycolytic blockade in tumor cells via Rad51 inhibition." (PMID 35875146, 2022). "Moreover, EBF1 regulates DNA repair in a dose-dependent manner by direct effects on RAD51, and combined loss of EBF1 and Pax5 predisposes patients to leukemia development." (PMID 32676457, 2020). "Here, we also found that both the drug-resistant subline HL60/ADR and radioresistant subline HL60/RX overexpressed the DNA repair pathway protein Rad51 after irradiation, suggesting that the increased ability to repair DNA lesions is a characteristic of radiation resistance in leukemia cells." (PMID 27105509, 2016). "To conclude, we propose the use of canine lymphoma/leukemia cells as a model to study DDR in cancer, with ATR, Claspin, Chk1, and Rad51 as promising targets for further analysis." (PMID 37655260, 2023). "Our experimental results show that after treatment with Stattic, the level of ATM mRNA in leukemia cells is lower, and after Stattic and VP-16 treatment of cells, the expression of BRCA1, BARD1, RAD51, and polδ in the HR pathway are all downregulated." (PMID 33796529, 2021). "In keeping with a role of USP15 in DDR, Rad51 protein levels were diminished by USP15 knockdown in MV4-11 and Kasumi-1 leukemia cells." (PMID 33378683, 2020). "In line with increased T-SCE frequency in NONO/SFPQ-depleted cells we observed an increased frequency of co-localization of TRF2 with Promyelocytic Leukemia (PML) nuclear bodies and co-localization of RAD51 with TRF2 in U-2 OS cells that were depleted for SFPQ." (PMID 30824709, 2019).
esophageal squamous cell carcinoma (13 papers, 2011 to 2025). Esophageal squamous cell carcinoma (ESCC) is a type of esophageal carcinoma (EC) that can affect any part of the esophagus, but is usually located in the upper or middle third. "For instance, Rad51 expression in esophageal squamous cell carcinoma was associated with advanced lymph node metastasis and unfavorable survival outcomes." (PMID 35875146, 2022). "Berberine pretreatment led to a significant downregulation of RAD51 in cells of esophageal squamous cell carcinomas." (PMID 36144625, 2022). "In esophageal squamous cell carcinoma, high Rad51 expression promotes tumor metastasis through the p38/Akt/Snail signaling pathway in TE8, CE81T, and KYSE70 cells." (PMID 35875146, 2022). "We next evaluated the RAD51 expression level in a panel of 86 human primary esophageal squamous cell carcinoma tissues by immunohistochemical staining." (PMID 21858113, 2011). "RAD51 induces tumor growth and metastasis in esophageal squamous cell carcinoma." (PMID 34716319, 2021). "Moreover, we overexpressed RAD51 in HepG2 cells with low RAD51 levels, and the RAD51 overexpression promoted cell proliferation, migration, or invasion, identical to a previous study in esophageal squamous cell carcinoma." (PMID 37175611, 2023). "In ESCC (esophageal squamous cell carcinoma), RAD51 expression indicated responses to chemotherapy." (PMID 38607586, 2024).
multiple myeloma (12 papers, 2013 to 2024). "We previously reported that exposure to SAHA induced the persistence of γ-H2AX nuclear foci in irradiated multiple myeloma cells, which was associated with the inhibition of RAD51-dependent HDR." (PMID 24367670, 2013). "In myeloma and Barrett’s esophageal adenocarcinoma, overexpression of RAD51 was found to enhance homologous recombination activity and then lead to pathological recombination events." (PMID 37858068, 2023). "Our previous investigations demonstrated elevated RAD51 expression in multiple myeloma and EAC cell lines and patient samples." (PMID 36428789, 2022). "Reis and co-workers reported that PNA–NLS targeting the transcription start site of RAD51, protein that mediated recombinational DNA repair and is overexpressed in multiple myeloma, sensitized multiple myeloma cells to melphalan treatment." (PMID 34367346, 2021). "In this study, we have demonstrated potentiation of apoptosis, marked reduction of viability, and decreased clonogenic survival of myeloma cells following exposure to relatively low doses of DOX together with a RAD51 inhibitor, B02." (PMID 25401086, 2014). "Didox treatment also suppresses RAD51 expression, a key DNA repair enzyme in myeloma cells and inhibits the upregulation of other DNA repair proteins in gliosarcoma cells." (PMID 25402485, 2014). "We previously reported high expression of RAD51 and increased homologous recombination (HR) rates in multiple myeloma (MM) cells, and showed that genomic instability and disease progression are commensurate with HR levels." (PMID 25401086, 2014). "This suggests that, to some extent, the amount of RAD51 protein was decreased independently of alterations in transcription for example by enhanced protein degradation as reported for myeloma cells treated with Vorinostat and irradiation." (PMID 24618637, 2014). "Our unpublished data in multiple myeloma also suggest a role of RAD51 in DNA replication." (PMID 36428789, 2022). "Of note, gene expression of APE2 and APE1 has been found up-regulated in multiple myeloma (MM) patients and MM cells, which may lead to dysregulation of HR via regulating Rad51 expression." (PMID 32111912, 2020). "Alone, doxorubicin treatment induced RAD51 foci formation in multiple myeloma cells, whereas pre-treatment with B02 blocked doxorubicin-induced RAD51 foci formation and increased the γ-H2AX foci number, due to unrepaired DSB caused by the doxorubicin treatment." (PMID 26610585, 2015). "Pre-treatments targeting Rad51 sensitize myeloma cells to DOX." (PMID 25401086, 2014). "RAD51 is thus a worthy therapeutic target for inclusion in chemotherapy cocktails to treat myeloma." (PMID 25401086, 2014). "This preferential toxicity of the DOX + B02 combination for MM cells supports our hypothesis that myeloma cells may be especially dependent on RAD51-mediated HR for survival." (PMID 25401086, 2014). "Data from our laboratory also show that exposure to nickel is associated with induction of a panel of HR genes, including (RAD51, RAD51 paralogs, RAD50, and RAD23) as well as leads to increased HR activity, genomic instability, and development of drug resistance in cancer (myeloma) cells." (PMID 26835419, 2016).
acute myeloid leukemia (11 papers, 2011 to 2023). Acute myeloid leukemia (AML) is a group of neoplasms arising from precursor cells committed to the myeloid cell-line differentiation. "Additionally, mutations in CHEK2 and BRCA2 have been linked to CLL and MDS, RAD51 in acute myeloid leukemia (AML) and MDS, MLH1 in MDS, and BRCA1 in AML." (PMID 34840720, 2021). "Acute myeloid leukemia (LAML) is the only one expressed lower RAD51 in cancer than in normal tissues." (PMID 35359409, 2022). "A study on acute myelogenous leukemia has indicated that HDAC inhibition by SAHA or PS results in the downregulation of RAD51 through miR-182 regulation." (PMID 34584069, 2021). "In this study, we demonstrate that suberoylanilide hydroxamic acid (SAHA) can increase radiosensitivity of acute myeloid leukemia (AML) cells through posttranslational modification of Rad51 protein responses and selective inhibition of the homology-directed repair (HDR) pathway." (PMID 24367670, 2013). "Mesothelioma (MESO) and uveal melanoma (UVM) have no comparable normal tissue, while acute myeloid leukemia (LAML) was the only cancer type that expressed lower RAD51 in cancer than in normal tissues." (PMID 35359409, 2022). "Expression of DNA damage repair proteins like 53BP1 and RAD51 was also downregulated following treatment with pevonedistat (NEDD8-activating enzyme inhibitor) and belinostat (HDACi) in acute myeloid leukemia (AML)." (PMID 32670880, 2020).
lung adenocarcinoma (11 papers, 2005 to 2024). A carcinoma that arises from the lung and is characterized by the presence of malignant glandular epithelial cells. "Interestingly, the expression of BRCA1, BRCA2, BLM and RAD51 was significantly associated with poor prognosis in lung adenocarcinoma." (PMID 37298484, 2023). "Since elevated RAD51 gene expression is commonly associated with cancers with defective HR repair pathways, we stratified tumors based on RAD51 mRNA expression to identify lung adenocarcinomas with elevated genomic instability." (PMID 33489883, 2020). "Kaplan-Meier analyses confirmed that patients with RAD51 High lung adenocarcinomas had significantly worse OS and DFS outcomes, compared to patients with RAD51 Low lung adenocarcinomas." (PMID 33489883, 2020). "MYB proto-oncogene like 2 (MYBL2) was the highest differentially expressed transcription factor upregulated in RAD51 High lung adenocarcinomas." (PMID 33489883, 2020). "It will be important to examine the efficacy of CHK1 inhibitors in combination with either RAD51 or POLQ small molecules when treating MYBL2 High lung adenocarcinomas." (PMID 33489883, 2020). "Afterwards, we detected the expression of RAD51 in lung adenocarcinoma tissues using IHC assays and statistically analyzed the correlation of RAD51 with clinical properties." (PMID 27566579, 2016). "Rad51 expression predicted the outcome of squamous cell cancer as well as adenocarcinoma of the lung." (PMID 15956972, 2005). "Next, we sought to identify the transcription factor(s) driving RAD51 High lung adenocarcinomas." (PMID 33489883, 2020). "To identify transcriptional programs associated with genomic instability and poor outcomes in lung adenocarcinoma, we stratified lung adenocarcinomas from The Cancer Genome Atlas (TCGA, TCGA Firehose Legacy, N = 517) on RAD51 mRNA expression using a quartile-based approach." (PMID 33489883, 2020). "Given the association between RAD51 and MYBL2 expression, we examined whether stratifying lung adenocarcinomas on MYBL2 mRNA expression alone could predict OS and DFS outcomes." (PMID 33489883, 2020). "Moreover, targeting RAD51, which is highly overexpressed in the lung adenocarcinoma tissues, can significantly increase the chemosensitivity of NSCLC cells to (−)-Guaiol both in vitro and in vivo." (PMID 27566579, 2016). "And mechanistically, we discovered that (−)-Guaiol significantly targeted RAD51 for degradation, which was highly overexpressed in the lung adenocarcinoma tissues, by inducing cell autophagy, thus leading to the double strand breaks (DSBs)-triggered cell apoptosis in NSCLC cells." (PMID 27566579, 2016).
serous ovarian cancer (11 papers, 2013 to 2025). "In RAD51C-silenced high-grade serous ovarian cancers, RAD51 re-expression was associated with an acquired loss of RAD51 promoter methylation during PARP inhibitors therapy." (PMID 34639169, 2021). "RAD51 protein expression is closely related to the sensitivity of neoadjuvant chemotherapy in advanced high-grade serous ovarian cancer." (PMID 41199843, 2025). "Combining with a PI3K/mTOR pathway inhibitor mitigated the CHK1 inhibitor-induced RAD51-mediated HR repair and augmented replication stress, leading to cell death in high-grade serous ovarian carcinoma." (PMID 35860572, 2022). "Rad51 suppression via microRNA-506 has been shown to sensitize serous ovarian cancer to DNA damaging drugs such as cisplatin and PARPi." (PMID 29340034, 2017). "High RAD51 expression facilitates rapid DNA repair, thereby conferring resistance to platinum-based chemotherapy and reducing chemosensitivity.In this study, RAD51 expression was significantly higher in advanced high-grade serous ovarian carcinoma compared to normal ovarian tissue." (PMID 41199843, 2025). "There are currently seven serous ovarian cancer patient samples listed with HELQ homozygous deletion, which is more than found for the RAD51 paralogs, except RAD51D." (PMID 24005565, 2013). "Furthermore, we analyzed the combined prognostic value of RAD51 expression and the KELIM score in predicting NACT sensitivity and prognosis in advanced high-grade serous ovarian cancer." (PMID 41199843, 2025).